SBK1 (SH3 domain binding kinase 1)
Description:
May be involved in signal-transduction pathways related to the control of brain development.
Synonyms: Sbk
Tractability: Small molecule: a high-quality ligand is known; it belongs to a druggable protein family. PROTAC: it is named in the literature on targeted protein degradation; ubiquitination databases record sites on it; a small molecule that binds it is known.
Target class: Enzyme; Other protein kinase NKF1 family; Kinase; Protein Kinase; Other protein kinase group
Gene: Protein-coding gene on chromosome 16 (28,259,246 to 28,323,849, forward strand). Ensembl gene ENSG00000188322.
Subcellular location: Cytoplasm
Gene Ontology:
Molecular function: protein serine/threonine kinase activity; ATP binding; protein kinase activity; protein serine kinase activity
Cellular component: cytoplasm
Genetic constraint (gnomAD): Loss-of-function variants: 11 observed, 15.96 expected, observed/expected ratio (o/e) 0.69, 90% interval 0.43 to 1.14. The synonymous counts are far from expectation, so gnomAD's model fits this gene poorly and the ratio says little. Missense variants: 467 observed, 465.66 expected, observed/expected ratio (o/e) 1, 90% interval 0.93 to 1.08. Synonymous variants: 308 observed, 215.72 expected, observed/expected ratio (o/e) 1.43, 90% interval 1.3 to 1.57.
Homologues: Orthologues: macaque SBK1 (98% identical), guinea pig SBK1 (96% identical), pig SBK1 (96% identical), rat Sbk1 (94% identical), chimpanzee SBK1 (94% identical), mouse Sbk1 (94% identical), tropical clawed frog sbk1 (69% identical), zebrafish sbk1 (55% identical), Drosophila melanogaster meng (28% identical), Drosophila melanogaster CG4945 (27% identical), Caenorhabditis elegans ikke-1 (22% identical), Caenorhabditis elegans Y39G8B.5 (21% identical). Paralogues in human: SBK3 (27% identical).
Diseases named in the same sentence as SBK1 in open-access papers:
SBK1 is named in the same sentence as 14 diseases in open-access papers, as found by Europe PMC text mining. Sharing a sentence is not in itself a finding about the gene and the disease. The quoted sentences say what the papers report.
lung carcinoma (4 papers, 2022 to 2024). "Consistently, we found that the DRAIC-associated downregulation of SBK1 is unfavourable for lung cancer survival." (PMID 39410631, 2024). "Of particular significance is that matched low expression of DRAIC and SBK1 mRNAs was associated with poor survival in both lung cancer types." (PMID 39410631, 2024). "Specifically, the mechanism by which the loss of SBK1 promotes lung cancer progression remains unknown." (PMID 39410631, 2024). "Furthermore, we explored the biological significance of the ceRNA network associated with DRAIC in lung cancer samples and identified SBK1 as an important component of this prognostic utility, potentially through miRNA-92a-1-5p." (PMID 39410631, 2024). "An increasing body of evidence suggests that FBP1, SBK1 and AURKA are associated with lung cancer progression." (PMID 37737707, 2023). "In contrast, we found that while SBK1 levels are downregulated in lung cancer patients who respond to anti-PD-1/PD-L1 immunotherapy, it is upregulated in melanoma responders." (PMID 36045683, 2022). "In both LUAD and LUSC, we observed a significant (p < 0.01) poor survival outcome for patients with a low DRAIC and low SBK1 expression compared to the rest of the samples, implying that the DRAIC-SBK1 axis (predicted ceRNA interaction) consistently promotes lung cancer progression." (PMID 39410631, 2024). "In summary, we show for the first time the pan-lung cancer prognostic role of DRAIC downregulation, potentially through dysregulated miR-92a-1-5p and the corresponding downregulation of SBK1." (PMID 39410631, 2024). "Further analysis showed that in lung cancer responders, CD69 was upregulated while SBK1 was downregulated and that in melanoma responders, both were upregulated." (PMID 36045683, 2022). "ROC analysis revealed that AUC values for the ability of CD69, SBK1 and RN7SK to predict response to PD-1/PD-L1 blockade immunotherapy in lung cancer were 0.754, 0.803, and 0.797, respectively, while in melanoma they were 0.637, 0.668, and 0.597, respectively." (PMID 36045683, 2022). "Meanwhile, both SBK1 and SLIT3 were found to play a vital role in lung cancer by miRNA or lncRNA." (PMID 35090416, 2022). "Analysis of TCGA lung cancer datasets (LUAD and LUSC) showed that while CD69 exhibited positive correlation with PD-1 and PD-L1, SBK1 exhibited negative correlation." (PMID 36045683, 2022).
cervical cancer (2 papers, 2021). A primary or metastatic malignant neoplasm involving the cervix. "Based on Kaplan‐Meier analysis, PCBP1-AS1 and four mRNAs (FAM222A, FHAD1, WDR62, and SBK1) were identified as potential prognostic factors for cervical cancer patients." (PMID 33833992, 2021).
melanoma (2 papers, 2021 to 2022). A malignant, usually aggressive tumor composed of atypical, neoplastic melanocytes. "Analysis of melanoma datasets (SKCM and UVM) showed that CD69 expression positively correlated with PD-1 and PD-L1 but the correlation between SBK1 and PD-1 or PD-L1 was not significant." (PMID 36045683, 2022).
ovarian carcinoma (2 papers, 2021 to 2022). A malignant neoplasm originating from the surface ovarian epithelium. "Wang found that SBK1 was dysregulated in several cancer tissues, especially in ovarian cancer, and showed that SBK1 played an important role during ovarian carcinogenesis." (PMID 33833992, 2021). "Another upregulated gene during heat stress based on the differential gene analysis is SBK1, which has been reported as part of widespread expression pattern involved in the protection of cells from apoptosis induced by the viral infection in ovarian cancer cells and promoting the cellular survival." (PMID 35986427, 2022).
colorectal carcinoma (1 paper, 2021). A malignant epithelial neoplasm that arises from the colon or rectum and invades through the muscularis mucosa into the submucosa. "SBK1 (SH3 Domain Binding Kinase 1), a novel missense mutational cancer gene in colorectal carcinoma, has also been previously found to be dysregulated in cancer." (PMID 34313788, 2021).
glioma (1 paper, 2014). A benign or malignant brain and spinal cord tumor that arises from glial cells (astrocytes, oligodendrocytes, ependymal cells). "In the unique module identified by DiME from the GBM glioma network, the RRAS oncogene, the SH3 domain binding kinase gene SBK1 and the transcription factor SOX8 involved in CNS development have the highest degrees of connectivity." (PMID 24523864, 2014).
lung adenocarcinoma (1 paper, 2023). A carcinoma that arises from the lung and is characterized by the presence of malignant glandular epithelial cells. "In addition, we will further investigate the impact of downregulating or promoting FBP1, SBK1, and AURKA expression in PC9 cells on lung adenocarcinoma in the future." (PMID 37737707, 2023).
Obesity (1 paper, 2025). Accumulation of substantial excess body fat. "Transcripts for several candidate genes for obesity were absent in the whole brain or absent in specific regions of the brain (Cyp17a1, Gdf15, Gpr151, Lmx1b, Olig3, Sbk1, Sim1, Skor1, Tnni3k)." (PMID 39920851, 2025).
retinoblastoma (1 paper, 2022). A malignant tumor that originates in the nuclear layer of the retina. "Another study reported that lncRNA ELFN1-AS1 promotes retinoblastoma progression by upregulating SBK1 expression." (PMID 36045683, 2022).
cancer (8 papers, 2014 to 2025). A tumor composed of atypical neoplastic, often pleomorphic cells that invade other tissues. "Indeed, SBK1 has been implicated in multiple cancers but exhibits cancer-specific expression and effects." (PMID 39410631, 2024). "CD69 and SBK1 are potential predictors of response to cancer immunotherapy using PD-1/PD-L1 blockade." (PMID 36045683, 2022). "IPS analysis demonstrated the ability of CD69 and SBK1 to predict PD-1/PD-L1 blockade responses in various cancers." (PMID 36045683, 2022). "In summary, our study indicates that CD69 and SBK1 expression levels can effectively predict cancer response to PD-1/PD-L1 blockade immunotherapy." (PMID 36045683, 2022). "Here, using bioinformatics analysis, we identified SBK1 as a potential predictor of response to PD-1/PD-L1 blockade cancer immunotherapy." (PMID 36045683, 2022). "To better understand the functions of CD69 and SBK1 in the tumor immune microenvironment, we carried out a comprehensive pan-cancer analysis using TCGA data." (PMID 36045683, 2022). "A correlation analysis of TCGA data from various cancers showed that CD69 expression correlated positively with immune checkpoint expression and immune infiltration, whereas SBK1 correlated positively or negatively with the same parameters, depending on the cancer type." (PMID 40989699, 2025). "We find that CD69 and SBK1 are differentially expressed in cancer patients who respond to PD-1/PD-L1 blockade when compared with non-responders, and that they are potential biomarkers of response to PD-1/PD-L1 blocking cancer immunotherapy." (PMID 36045683, 2022). "However, the relationship between EGFR mutations and Gefitinib target genes (FBP1, SBK1, and AURKA) warrants further investigation, and cancer tissues were collected to confirm the relationship between the risk model and nomogram and the prognosis of LUAD patients in the future." (PMID 37737707, 2023). "SBK1 is dysregulated in multiple cancer types and may display a broad range of cellular functions." (PMID 24523864, 2014). "Correlation analysis revealed that in various TCGA cancer datasets, CD69 expression level correlated positively with most immune checkpoints and tumor-infiltrating immune cells, while SBK1 expression level correlated negatively with infiltrating immune cells." (PMID 36045683, 2022).
tumor (5 papers, 2016 to 2025). "Our analysis also revealed that SBK1 upregulation negatively correlates with most tumor-infiltrating immune cells." (PMID 36045683, 2022). "This analysis found that CD69 mRNA levels positively correlated with immune cell infiltration levels in most tumors, and that SBK1 mRNA levels negatively correlated with tumor infiltration by most immune cells." (PMID 36045683, 2022). "We then compared the mRNA levels of CD69 and SBK1 in tumor versus normal tissues using TCGA and GTEx datasets." (PMID 36045683, 2022). "The results showed that the expression of PCBP1-AS1, FAM222A, FHAD1, WDR62, and SBK1 was significantly correlated with tumor clinical stage, pathologic TNM, and lymphatic invasion (p < 0.05)." (PMID 33833992, 2021). "Thus, we speculate that SBK1 affects the immune landscape by modulating lipid metabolism in the tumor microenvironment, which warrants further investigation." (PMID 36045683, 2022). "FCHSD1 may functionally cooperate with interacting genes (e.g., SBK1, ITSN2, and FNBP4) to collectively drive tumor malignancy, thus warranting further mechanistic investigations to elucidate these molecular interactions." (PMID 40535123, 2025). "FCHSD1 may functionally interact with SBK1, ITSN2, and FNBP4 to collectively regulate malignant tumor progression." (PMID 40535123, 2025).
SBK1 also shares sentences with these, for which no sentence is quoted: B-cell lymphoma (1 paper); pituicytoma (1); viral infection (1).